PAQR7 (progestin and adipoQ receptor family member 7)
Description:
Plasma membrane progesterone (P4) receptor coupled to G proteins. Seems to act through a G(i) mediated pathway. May be involved in oocyte maturation. Involved in neurosteroid inhibition of apoptosis. Also binds dehydroepiandrosterone (DHEA), pregnanolone, pregnenolone and allopregnanolone.
Synonyms: mSR; MPRA; PGLP
Tractability: Antibody: UniProt places it where antibodies can reach, with medium confidence; UniProt predicts a signal peptide or a membrane-spanning region; its Gene Ontology location is reachable by antibodies, with medium confidence. PROTAC: ubiquitination databases record sites on it.
Gene: Protein-coding gene on chromosome 1 (25,861,484 to 25,875,874, reverse strand). Ensembl gene ENSG00000182749.
Subcellular location: Cell membrane
Subcellular location (Human Protein Atlas): Cytosol
Gene Ontology:
Molecular function: protein binding; nuclear steroid receptor activity; steroid binding
Biological process: response to steroid hormone; nuclear receptor-mediated steroid hormone signaling pathway
Cellular component: plasma membrane; membrane
Genetic constraint (gnomAD): Loss-of-function variants: 14 observed, 26.1 expected, observed/expected ratio (o/e) 0.54, 90% interval 0.35 to 0.84. The upper end of that interval is the gene's LOEUF score, 0.84, which puts it in group 3 of 6, group 1 being the genes least tolerant of losing a copy. Missense variants: 351 observed, 466.11 expected, observed/expected ratio (o/e) 0.75, 90% interval 0.69 to 0.82. Synonymous variants: 189 observed, 208.85 expected, observed/expected ratio (o/e) 0.9, 90% interval 0.8 to 1.02.
Homologues: Orthologues: chimpanzee PAQR7 (99% identical), macaque PAQR7 (98% identical), pig PAQR7 (92% identical), dog PAQR7 (91% identical), rabbit PAQR7 (90% identical), guinea pig PAQR7 (85% identical), rat Paqr7 (84% identical), mouse Paqr7 (82% identical), zebrafish paqr7b (55% identical), Caenorhabditis elegans K11C4.2 (19% identical), Drosophila melanogaster AdipoR (17% identical), Caenorhabditis elegans paqr-1 (16% identical). Paralogues in human: PAQR8 (47% identical), PAQR6 (26% identical), PAQR5 (24% identical), PAQR9 (21% identical), ADIPOR2 (21% identical), ADIPOR1 (19% identical), PAQR3 (18% identical), PAQR4 (18% identical), MMD2 (12% identical), MMD (10% identical).
Diseases named in the same sentence as PAQR7 in open-access papers:
PAQR7 is named in the same sentence as 36 diseases in open-access papers, as found by Europe PMC text mining. Sharing a sentence is not in itself a finding about the gene and the disease. The quoted sentences say what the papers report.
breast carcinoma (16 papers, 2009 to 2025). "Assessment of mPRs expression demonstrated increased PAQR7 expression in breast tumor tissue compared to normal tissue, with statistical significance from the entire collection, supporting previous observations of increased PAQR7 RNA expression in breast cancers." (PMID 35971177, 2022). "Human breast cancer cells (MCF-7) served as positive control for establishing the immunohistochemical staining for PGRMC1, PAIRBP1, and PAQR7." (PMID 27340667, 2016). "Overall, expression levels of all three CCM proteins are upregulated in breast tumors compared to normal tissues, in concordance with increased expression of PAQR7, suggesting a coordinated relationship between the CSC and mPRs during breast cancer tumorigenesis." (PMID 35971177, 2022).
lung adenocarcinoma (5 papers, 2020 to 2025). A carcinoma that arises from the lung and is characterized by the presence of malignant glandular epithelial cells. "We used the HPA, an online comprehensive bioinformatics analysis platform, to study the relationship between mPRα mRNA expression level (the corresponding gene name is PAQR7) and the survival prognosis of patients with lung adenocarcinoma." (PMID 32529777, 2020).
glioblastoma (4 papers, 2020 to 2024). The most malignant astrocytic tumor (WHO grade IV). "Additionally, PAQR7 has been proven to stimulate cell proliferation and motility in human glioblastoma cells, implicating it in glioblastoma progression." (PMID 39742277, 2024).
endometrial cancer (3 papers, 2020 to 2022). Primary or metastatic malignant neoplasm involving the endometrium (mucous membrane that lines the endometrial cavity). "Human ovarian cancer cells were the first ones to show mPR activity, but the prognostic potential of PAQR7/8 downregulation was established in endometrial cancers in 2018." (PMID 34572596, 2021). "It has been recently reported that the expression of PAQR7 and the respective protein content are decreased in endometrial cancer compared to adjacent unaffected tissue." (PMID 32733932, 2020). "In addition, PAQR7 and PAQR8 expression and the respective protein content are decreased in endometrial cancer compared to adjacent nonaffected endometrium, whereas mPRγ protein content is increased in endometrial cancer tissue." (PMID 32733932, 2020).
endometriosis (3 papers, 2020 to 2025). The growth of functional endometrial tissue in anatomic sites outside the uterine body. "The results of the present study showed that both the expression of PAQR7 and PAQR5, as well as the protein content of mPRα and mPRβ, was significantly reduced in the ectopic endometrium of patients with endometriosis compared to the endometrium of women without the disease." (PMID 32733932, 2020). "Using RT-qPCR, we observed that the expression of PAQR7, PAQR8, PAQR5, and PAQR6 genes was significantly downregulated in the eutopic endometrium of patients with endometriosis compared with the endometrium of women without the disease." (PMID 32733932, 2020). "The analysis of gene expression showed that PAQR7 and PAQR5 expression was lower in both eutopic and ectopic endometrium as compared to the endometrium of women without endometriosis, whereas the expression of PAQR8 and PAQR6 was only reduced in eutopic endometrium." (PMID 32733932, 2020).
breast tumor (2 papers, 2013 to 2022). "Our data also correlated expression between CCM proteins and PAQR7 in breast tumors." (PMID 35971177, 2022).
adenomyosis (1 paper, 2022). The growth of endometrial tissue inside the muscular wall of the uterine corpus. "The expression of PAQR7 (mPRα) and PAQR8 (mPRβ) was significantly upregulated in adenomyosis compared to normal myometrium." (PMID 35956024, 2022).
astrocytoma (1 paper, 2016). "Recently, PAQR7 expression has been described in human astrocytoma cell lines U-87 and U-251." (PMID 27340667, 2016).
liver cancer (1 paper, 2023). An epithelial or non-epithelial malignant neoplasm that arises from the liver. "Our findings revealed altered expression of several CmPn members (including CCM1/3 and PAQR7/8) between normal and tumor tissues and among different liver cancer subtypes, which was also observed for PGRMC1." (PMID 36980321, 2023). "When comparing protein expression of key CmPn players within liver cancer subtypes, PAQR7, PGRMC1, and nPRs proteins were significantly differentially expressed only when comparing HCC to all other subtypes, which was also observed in our preliminary TCGA analysis between HCCs and CCAs." (PMID 36980321, 2023). "In addition, altered expression of all three members of the CSC, along with PAQR7, has been observed during the early stages of tumorigenesis in liver cancer." (PMID 36980321, 2023). "Furthermore, we compared CCM3 and PAQR7 protein expression between HCC and cHCC-CCA, since cHCC-CCA is known to be a biphenotypic liver cancer subtype, presenting hepatocytic and biliary differentiation." (PMID 36980321, 2023).
ovarian dysfunction (1 paper, 2024). The inability of the ovaries to function. "Since the knockout of Paqr7 caused ovarian dysfunction in mice, we evaluated whether the expression of PAQR7 was related to DOR, a common disease of ovarian dysfunction." (PMID 38317224, 2024).
pituitary adenomas (1 paper, 2022). "Another lncRNA, called C5orf66-AS1, regulates several genes, including PAQR7, a progesterone receptor that causes a progesterone A-B receptor-independent reduction in GnRH, whose expression has been found to have a role in progression and invasion of null-cell pituitary adenomas." (PMID 35432200, 2022).
prostate carcinoma (1 paper, 2021). A carcinoma that arises from epithelial cells of the prostate gland. "PAQR6 was upregulated about 2-fold, and PAQR7/8 was downregulated more than 1.5-fold in prostate cancers compared to normal prostatic tissues." (PMID 34572596, 2021).
skin cancer (1 paper, 2016). "Given that the increased systemic estrogen and progesterone associated with pregnancy does not typically result in skin cancer or significant pathology in other tissues, we think it likely that the specific GPER and PAQR7 agonists will be well-tolerated." (PMID 27115344, 2016).
cancer (7 papers, 2011 to 2024). A tumor composed of atypical neoplastic, often pleomorphic cells that invade other tissues. "In addition, we found that in OVCAR-3 cells and patient tissues, expression of PAQR7 was lower in cancer cells than in normal cells, with a significance level of p ≤ 0.01 and p ≤ 0.05, respectively." (PMID 39464509, 2024).
tumor (6 papers, 2011 to 2024). "Expression of mRNA encoding PAQR7 and PAQR8 in a panel of OC cell lines was below the qPCR detection limit and was downregulated in tumour tissue samples, whereas high expression of PGRMC1 and PAQR4 mRNA was observed in rare subtypes of OC cell lines." (PMID 39464509, 2024). "Moreover, expression of PAQR7 mRNA did not correlate with tumour stage or with survival rates." (PMID 39464509, 2024).
PAQR7 also shares sentences with these, for which no sentence is quoted: infection (11 papers); ovarian carcinoma (3); breast invasive cancer (2); latent infection (2); Parkinson disease (2); adrenal pheochromocytoma (1); colorectal cancer (1); cutaneous leishmaniasis (1); cystitis (1); gingivitis (1); hepatic angiosarcoma (1); leukemia (1); lung squamous cell carcinoma (1); malaria (1); nonsmall cell lung cancer (1); pneumonia (1); pyelonephritis (1); Sepsis (1); toxoplasmosis (1); triple-negative breast carcinoma (1); undifferentiated pleomorphic sarcoma (1).